ALB (albumin)
Diseases named in the same sentence as ALB in open-access papers (continued):
Sharing a sentence is not in itself a finding about the gene and the disease.
liver failure (206 papers, 2003 to 2026). A liver disease characterized by the liver losing or has lost all of its function. "Clinical data have already shown increased liver failure markers such as a high albumin-bilirubin score as independent risk factors for mortality in patients with severe AS." (PMID 40409472, 2025). "Typical clinicopathological alterations associated with liver failure in dogs include decreased albumin, urea, glucose, and coagulation factors, alongside elevated total bilirubin, ammonium, and bile acids." (PMID 39409835, 2024). "Taken together, free bilirubin, DB/TB and indirect bilirubin-albumin ratio are risk factors for neurological dysfunction and nerve damage in patients with liver failure." (PMID 38020137, 2023). "Hepatic encephalopathy which is a frequent and grave complication of liver failure, is associated with multiple biochemical changes like high serum ammonia, mercaptan and phenol levels, low albumin levels and derangements in electrolytes." (PMID 37363515, 2023). "If we consider low albumin as a sign of liver failure, it can be argued that liver problems cause higher mortality than kidney disease (high creatinine levels)." (PMID 37308964, 2023). "We also found that albumin was a risk factor for the prognosis of liver failure and a predictor of morbidity and mortality." (PMID 35811816, 2022). "Albumin levels are often lower in patients with hepatic insufficiency, which was also associated with higher mortality in the patients with hepatobiliary disease included in this study." (PMID 31467670, 2019). "Persistent activation of Nrf2 due to sequestration of Keap1 into Sqstm1-positive structure causes hepatomegaly and liver failure in Atg7f/f;Albumin-Cre and Atg5f/f;Albumin-Cre mice." (PMID 26483381, 2015). "In conditions such as protein-losing nephropathy or hepatic insufficiency, albumin half-life may be significantly altered, potentially causing GA values to under- or overestimate actual glycemia." (PMID 40723467, 2025). "Previous studies have reported that pre-albumin, globulin, and neutrophilic granulocytes are associated with fungal infection in patients with liver failure." (PMID 38601929, 2024). "Indeed, most of the common toxins associated with liver failure are albumin dependent, hydrophobic molecules." (PMID 37675369, 2023). "The Mayo risk score majorly includes bilirubin, albumin, age, prothrombin time, and edema degree, where both elevated total bilirubin and prolonged prothrombin time are linked to liver failure." (PMID 36159788, 2022). "It is known that liver failure is associated with a decrease in serum albumin and cholesterol levels, further studies are required to figure out whether the elevated albumin and cholesterol is a sign of improved hepatocyte synthesis during TAF treatment." (PMID 34126939, 2021). "The decreased albumin production could be due to a hepatic insufficiency, while the increased albumin loss could be due to a protein-losing nephropathy, as well as acute or chronic blood loss, and it should be excluded diagnostically." (PMID 34679072, 2021). "A recent cohort study (TRIBE–AKI Consortium) in adults used urinary biomarkers (tubular injury markers [NGAL, IL-18, KIM-1, L-FABP], tubular function markers [FeNa] and glomerular injury markers [albumin]) to differentiate between various causes of AKI in liver failure." (PMID 29497824, 2019). "Here, our clinical case-control study reveals for the first time that the IBil/albumin ratio is the most powerful risk factor for HE in patients with liver failure, suggesting that free bilirubin may be a pathogenic factor for the neurological impairment of HE." (PMID 34527681, 2021). "Conventional dialysis therapies in patients with hepatic failure are insufficient, involving the use of modalities whose mechanism allows for the extraction of hydrophobic and protein-bound solutes such as albumin." (PMID 40656314, 2025).
liver failure (continued). "We propose a novel approach to enhance the accuracy of predicting the prognosis of liver failure patients by introducing a ratio of blood lactate to serum albumin." (PMID 40155840, 2025). "In most studies, AIMS65 (which incorporates albumin level and an indicator of liver failure) appears to be superior to the Rockall score or GBS; few studies have demonstrated the superiority of both RS and GBS, however." (PMID 40863238, 2025). "The independent risk factors (history of ulcer disease, HB, PLT, ALB, heart rate, SBP, liver failure, CRP) screened-out by the multivariate logistic risk regression model were ranked according to their importance by machine learning using R language." (PMID 41585275, 2025). "The CCL4-induced liver failure group had considerably greater (p < 0.0001) serum albumin levels than the control saline-treated group, whereas total protein serum levels were significantly lower." (PMID 38413963, 2024). "The patient was treated with supportive measures for liver failure with fluid resuscitation and intravenous albumin." (PMID 39335578, 2024). "The concurrent decrease in serum albumin and urea concentrations and the increase in bile acids concentration is suggestive of hepatic failure, reflecting diminished liver synthesis and conjugations capability." (PMID 39409835, 2024). "Conversely, liver failure is characterized by alterations in the metabolites produced, metabolized, or excreted by the liver, such as albumin, urea, total bilirubin, ammonium, bile acids, and coagulation factors." (PMID 39409835, 2024). "Recently, a retrospective case–control study showed that the indirect bilirubin-albumin ratio is an independent factor of hepatic encephalopathy in patients with liver failure (aOR:1.63, 95% CI: 1.32~2.00, p < 0.001)." (PMID 38020137, 2023). "The experimental components consisted of replacing traditional adsorbent materials with albumin-functionalized silica microspheres due to their capacity to adsorb bilirubin, one of the toxins responsible for liver failure." (PMID 37370637, 2023). "Artificial non-biological systems were based on the general concept of albumin dialysis and the removal of albumin-bound toxins from blood and/or plasma that accumulate during liver failure." (PMID 37685652, 2023). "In liver failure, the content of free bilirubin increases due to increased indirect bilirubin, insufficient quantity and/or, decreased binding capacity of albumin." (PMID 38020137, 2023). "This applies to categories “albumin”, “ascites”, “Child–Pugh”, “hepatitis”, “hepatic failure”, “liver insufficiency”, “porphyria” and “transaminases”." (PMID 35407541, 2022). "When the use of human-induced Hepatocytes (hiHeps) was investigated in mouse and pig models of liver failure, liver failure markers were decreased, hepatocyte function indicated by albumin synthesis improved, and survival time increased." (PMID 35882727, 2022). "Age, IL-2, ALB, γ-GT, ALP, TBIL, Hb, TBA, WBC, and PLT, as well as anti-Sp100, were found to be independent risk factors in PBC patients with liver failure." (PMID 36159788, 2022). "It is based on an albumin-enriched dialysis, allowing removal of albumin-bound toxins that accumulate during liver failure or, cases of cholestasis." (PMID 36123713, 2022). "The significant decrease in serum albumin and total protein levels monitored in mice with Ehrlich solid tumours is equivalent to liver failure, manifested as decreased biosynthetic capacity." (PMID 35844382, 2022). "Serum urea, creatinine, gamma-glutamyl transferase, albumin, and electrolyte levels were quantified as the markers of acute renal and liver failure." (PMID 34504408, 2021). "Similar results were obtained in studies utilizing severe liver failure models in which unchanged levels of transaminases and albumin were also detected in both MSC-treated and control groups." (PMID 33919123, 2021).
liver failure (continued). "They reported that low serum albumin, liver failure, and higher acute physiology and chronic health evaluation (APACHE) II scores were associated with higher AKI rates." (PMID 33659105, 2021). "Liver compromise can lead to elevations in serum enzyme activities and an impaired albumin synthesis occurring in hepatic failure." (PMID 34452320, 2021). "In liver failure, fractional synthesis rate is mainly decreased because production of albumin is affected by liver function." (PMID 33925831, 2021). "Liver failure results in decreased rates of albumin, pre-albumin, retinol binding protein and transferrin." (PMID 31936597, 2020). "Intravenous human albumin, oral vitamin K, and cholestyramine were administered for liver failure and leflunomide overdosage, respectively." (PMID 32019572, 2020). "In turn, albumin levels were found to be decreased in a tramadol-induced fatal overdose with liver failure." (PMID 32664348, 2020). "These variables were age, AIDS, leukemia, metastatic tumor, hepatic failure, lowest albumin, and FiO2." (PMID 31576250, 2019). "The GA search identified seven important variables, which were age, AIDS, leukemia, metastatic tumor, hepatic failure, lowest albumin, and FiO2." (PMID 31576250, 2019). "Circulating albumin has been considered as an estimation tool for hepatic insufficiency as a component of the Child-Pugh classification." (PMID 31821367, 2019). "These systems are based on the concept of albumin dialysis and therefore on the capacity to remove the albumin-bound toxins that accumulate in liver failure." (PMID 30443736, 2018). "We aimed to explore the capability of the albumin-bilirubin (ALBI) grade to predict post-hepatectomy liver failure (PHLF) and long-term survival after hepatectomy for HCC patients with different Barcelona Clinic Liver Cancer (BCLC) stages." (PMID 30326907, 2018). "Adsorption of albumin-bound toxins was assessed with batch experiments using human plasma with high level bilirubin of liver failure patients in vitro." (PMID 28149527, 2017). "Albumin-Cre (AlbCre)-induced genetic disruption of Sirt1 in hepatocytes also led to significant protection against GalN/LPS-induced liver failure." (PMID 27711079, 2016). "The aim of extracorporeal albumin dialysis (ECAD) is to reduce endogenous toxins accumulating in liver failure." (PMID 26728364, 2016). "Human serum albumin (HSA) infusion has been shown to reduce mortality in liver failure patients with spontaneous bacterial peritonitis and hepatorenal syndrome and following large volume paracentesis." (PMID 25937432, 2015). "Liver function detained from hepatocytes from extraordinary toxic exposures, Patients who appeared by a lowered albumin and an elevated bilirubin levels ignited the onset of liver failure, leading to a poor clinical outcome." (PMID 26602960, 2015). "Albumin serves as a carrier for molecules of low water solubility, including several toxic substances that accumulate in liver failure (e.g., bilirubin) and some drugs (e.g., warfarin, phenylbutazone, clofibrate, and phenytoin)." (PMID 23217363, 2012). "Most toxins produced by liver failure bind to albumin, and traditional hemodialysis cannot effectively remove the toxicity for acute liver failure patients." (PMID 21829646, 2011). "Our study found that the levels of Af-Gc globulin in liver failure patients had a significantly positive relationship with ALB, ALT, AST, CHE, that is to say, the level of Af-Gc can also be used to evaluate the degree of hepatic injury." (PMID 27942277, 2009). "In liver failure cohort, plasma Af-Gc globulin was significantly positive correlated with ALB, ALT, AST and CHE (P was 0.001, 0.001, 0.001, < 0.001, respectively)." (PMID 27942277, 2009). "This case is, to our best knowledge, the first report of a multi-organ failure secondary to inhalation of methylene-bis-thiocyanate and one of the first reports of the successful use of MARS albumin dialysis in hepatic failure due to intoxication." (PMID 16608508, 2006).
liver failure (continued). "• MARS and Prometheus are cell-free extracorporeal liver support systems providing elimination of albumin-bound as well as water-soluble toxins that accumulate in liver failure." (PMID 17156425, 2006). "This liver failure affected protein metabolism and lowered serum albumin." (PMID 41359068, 2025). "In the context of hepatic dysfunction, the removal of cytokines and hydrophobic, albumin‐bound hepatic toxins, such as bilirubin, bile acids, and amino acids, may have a beneficial effect on the clinical course of patients in liver failure." (PMID 37335451, 2024). "Both albumin and urea are synthesized in the liver, and their concentrations may decrease in patients with severe hepatic failure." (PMID 39057982, 2024). "Circulating RIPK3 and albumin levels may have the potential to reflect chronic hepatitis or liver failure prior to hospitalization, and further studies are needed to differentiate ALF from ACLF." (PMID 37640752, 2023). "As a result, the percentage of carbamylated albumin represents a valuable biomarker of protein carbamylation—even though its half-life and concentration can be influenced by various pathophysiological conditions like liver failure and denutrition." (PMID 37532908, 2023). "In ACLF, serum albumin levels decrease due to liver failure, as reported in literature." (PMID 36776389, 2022). "Conditions such as hypervolemia, proteinuria or liver failure, which may decrease serum albumin levels in COVID-19 pneumonia, should be treated." (PMID 35507997, 2022). "However, the protein-binding rate of drugs in patients with liver failure decreases due to the reduction in albumin synthesis, decline in albumin activity, or conformational changes in albumin." (PMID 35955643, 2022). "In liver failure, water-soluble toxins (e.g., ammonia and mercaptans) and albumin-bound toxins (e.g., bilirubin, bile acids, aromatic amino acids, and fatty acids) may accumulate and cause encephalopathy and dysfunction in other organs." (PMID 35882727, 2022). "In summary, patients with liver failure with a higher IBil/albumin ratio are prone to HE." (PMID 34527681, 2021). "The blood albumin concentration decreases during liver failure and chronic inflammatory diseases." (PMID 34076758, 2021). "In liver failure, serum Bf may increase due to increased total bilirubin, insufficient albumin, and/or abnormal albumin binding capacity." (PMID 34527681, 2021). "Albumin dialysis is already used to remove endotoxin in patients with liver failure and might be used to test whether lowering endotoxin is beneficial for neurodegeneration, but applying albumin dialysis for several years would be challenging." (PMID 31519175, 2019). "The results showed that the most important predictors of mortality included immunodeficiency, metastatic tumor, hepatic failure, residing at home independently, FiO2, chronic dialysis, ventilation mode, albumin, age, highest glucose, highest bilirubin, minute ventilation volume and admit source." (PMID 31576250, 2019). "In the current study, we observed increased TGFβ1 expression localized primarily to hepatocyte populations due to its co-localization with CK8, supporting findings from our previous work demonstrating TGFβ1 co-localization> with albumin during AOM-induced liver failure." (PMID 30940161, 2019). "Based on this fact, the removal of lipophilic, albumin-bound substances such as bilirubin, bile acids, metabolites of aromatic amino acids, medium-chain fatty acids and cytokines should be beneficial to the clinical course of a patient in liver failure." (PMID 29364955, 2018). "The reduction of albumin levels is partly a result of renal excretion due to glomerular damage produced during the course of the disease and the low production by the liver in cases of liver failure." (PMID 29789784, 2018). "Many accumulating substances in liver failure are transported bound to albumin." (PMID 26728364, 2016).
liver failure (continued). "Thus, one study found an initial difference of 10 mg/dL between the total and conjugated bilirubin in patients with liver failure undergoing albumin dialysis." (PMID 27313607, 2016). "Moreover in liver failure, the detoxifying function of albumin, which is critical to recovery from liver injury, is irreversibly destroyed." (PMID 25937432, 2015). "Also suggestive of liver failure, average ALB values were significantly decreased when comparing the pre-infection values to post values for both surviving and euthanized animals (p = 0.0003 and 0.0045 respectively)." (PMID 22164263, 2011). "Albumin dialysis results in a significant decrease in circulating phenolic aromatic amino acids and improvement of hepatic encephalopathy in patients with severe liver failure." (PMID 19175915, 2009). "Therefore, the aim of the current study was to assess the effect of albumin dialysis on hepatic encephalopathy and on the circulating levels of amino acids and ammonia in patients with severe liver failure." (PMID 19175915, 2009). "However, in the case of patients with both a low albumin (<30 g dl−1) and a high bilirubin (>50 μmol l−1), denoting the onset of liver failure, the median survival was only 0.6 months (range 0.16–1.57)." (PMID 12865918, 2003). "Besides, server inflammation often combined with liver failure, which could decrease serum albumin mass because albumin synthesis rate is mainly decreased in liver failure." (PMID 39250466, 2024). "Despite the absence of decreased albumin and urea, this finding may suggest an initial stage of liver failure, possibly associated with extensive liver damage." (PMID 39409835, 2024). "Intraliver or intrahepatic injection of generated hepatocytes to patients or animal with liver failure or partial hepatectomy could upregulate hepatic genes expression, increase serum ALB concentration, enhance liver regeneration, and make long longevity of transplant recipient." (PMID 36685673, 2023). "However, HSC cell transplantation may serve to bridge the time until organ transplantation takes place or can be given concomitantly with artificial liver support systems which remove albumin-bound toxins that accumulate in liver failure." (PMID 35954155, 2022). "The decrease in albumin levels may be due to inflammation or liver failure." (PMID 29463041, 2018). "Cluster 5 presents low albumin and serum sodium, accompanied by low AFP, suggesting a transitional stage of liver failure." (PMID 41536859, 2026). "As the patient experienced worsening hepatic failure, SPAD was added to the CRRT, utilizing 3% albumin." (PMID 40656314, 2025). "They use laboratory parameters, including ALP, AST, age at diagnosis, TB, albumin (ALB), and platelets (PLT), to predict response to treatment (URS) or the occurrence of complications, such as liver failure, and the need for liver transplantation." (PMID 41303284, 2025). "It has been found that patients with HH have lower cholesterol and triglyceride levels, and that their hepatic insufficiency is more advanced, exhibiting higher INR values, lower serum albumin levels, and higher bilirubin values." (PMID 39797295, 2025). "Liver failure was induced by hepatotoxic drugs, such as APAP, LPS, D-GalN, CCL4, human serum albumin (HSA), concanavalin-A, and TNF, or surgical simulation including cecal ligation puncture, partial hepatectomy, and bile duct ligation." (PMID 38172209, 2024). "There was a significant (p < 0.0001) decline in serum albumin levels after treatment with tadalafil and L. sativum alone or in combination with CCL4-induced liver failure, with a greater drop in the L. sativum-treated group and combination-treated group." (PMID 38413963, 2024). "The 99mTc-galactosyl human serum albumin (Tc-99m GSA) scintigraphy evaluates the future remnant liver function, which is an important prognostic factor for post-hepatectomy liver failure (PHLF)." (PMID 37609100, 2023).